RNU6-495P (RNA, U6 small nuclear 495, pseudogene)
Gene: Small nuclear RNA gene on chromosome 22 (41,377,177 to 41,377,283, reverse strand). Ensembl gene ENSG00000199865.
Homologues: Orthologues: chimpanzee U6 (97% identical), macaque U6 (93% identical), mouse Gm24584 (86% identical), rat U6 (86% identical), pig U6 (85% identical), rat U6 (85% identical), dog U6 (84% identical), rabbit U6 (84% identical), dog U6 (82% identical), pig U6 (80% identical), guinea pig U6 (79% identical). Paralogues in human: RNU6-48P (90% identical), RNU6-187P (89% identical), RNU6-1075P (87% identical), RNU6-1124P (87% identical), RNU6-12P (87% identical), RNU6-13P (87% identical), RNU6-25P (87% identical), RNU6-29P (87% identical), RNU6-32P (87% identical), RNU6-33P (87% identical), RNU6-41P (87% identical), RNU6-44P (87% identical), and 1283 more.